G3BP1 (G3BP stress granule assembly factor 1)
Diseases named in the same sentence as G3BP1 in open-access papers (continued):
Sharing a sentence is not in itself a finding about the gene and the disease.
viral infection (continued). "During virus infection, SGs can be inhibited by knocking out PKR, inhibiting both translation inhibition and SG formation, or by knocking out nucleating factors like G3BP1, which only inhibits the physical formation of SGs and not translation inhibition." (PMID 37983241, 2023). "The antiviral effect was not restricted to the laboratory adapted DENV-2 NGC as G3BP1, G3BP2 and CAPRIN1 had antiviral activity against the clinical DENV-2 isolate PR1940 as well as the related yellow fever vaccine strain (YFV-17D)." (PMID 24992036, 2014). "Surprisingly, in the absence of PABPC1, the formation of G3BP1 foci was abrogated in SeV-infected cells but not after arsenite treatment or poly(I:C) transfection, suggesting that PABPC1 has another important function in promoting SG formation exclusively during viral infection." (PMID 36781883, 2023).
breast carcinoma (30 papers, 2011 to 2025). "Ras-GTPase-activating protein SH3 domain-binding protein 1 (G3BP1) and protein kinase C, Zeta isoform (PKCζ) are oncogenes implicated in numerous cancers, including breast cancer." (PMID 36330442, 2022). "Several recent studies have found that G3BP1 is significantly associated with the development of cancers, such as breast cancer and gastric cancer." (PMID 34967276, 2022). "In this study, we found that high expression of G3BP1 was associated with metastasis in breast cancer patients by immunohistochemical staining, and metastasis of tumors is the main cause of patient death." (PMID 36330442, 2022). "Furthermore, high expression of G3BP1 was associated with lower survival rates in breast cancer patients." (PMID 36330442, 2022). "In addition, by analyzing the clinicopathological information we found that G3BP1 high expression was associated with metastasis of breast cancer patients." (PMID 36330442, 2022). "In addition, we found that G3BP1 expression was associated with survival in breast cancer patients using database, so G3BP1 may be a prognostic marker for breast cancer." (PMID 36330442, 2022). "In tumor contexts, reduced G3BP1 expression promotes mTORC1-mediated breast cancer cell motility and correlates with unfavorable clinical prognosis." (PMID 41450825, 2025). "G3BP1 has been reported to regulate the activity of the Wnt/β-Catenin signaling pathway in esophageal cancer, colon cancer, and breast cancer." (PMID 38906857, 2024). "Silencing G3BP1 expression in vivo can inhibit breast cancer cellcell migration, whereas G3BP1 knockout in mice can inhibit distant metastasis of tumors." (PMID 37179344, 2023). "G3BP1 can also inhibit the phosphorylation and degradation of β-catenin and promote the proliferation of human breast cancer cell via interaction with GSK-3β." (PMID 37179344, 2023). "We observed that the reduction of G3BP1 expression significantly inhibited the establishment of cell polarity in the directed movement of breast cancer cells." (PMID 36330442, 2022). "To verify the importance of G3BP1 in breast cancer, we examined the expression of G3BP1 in seven benign breast tissues and 68 breast invasive ductal carcinoma tissues by immunohistochemistry." (PMID 36330442, 2022). "The results showed that G3BP1 expression was increased in most tumors, and significantly higher in breast cancer than normal in 112 paired samples." (PMID 36330442, 2022). "The results showed that the reduction of G3BP1 expression significantly inhibited EGF-induced actin polymerization in breast cancer cells." (PMID 36330442, 2022). "In this study, we found that knockdown of G3BP1 affected the proliferation and invasive capacity of breast cancer cells." (PMID 36330442, 2022). "Chemotaxis assays showed that reduced expression of G3BP1 significantly inhibited the epidermal growth factor (EGF)-induced chemotactic motility of breast cancer cells." (PMID 36330442, 2022). "We then found that the RNA and protein expression levels of G3BP1 were significantly upregulated in primary breast cancer compared to normal individuals by the UALCAN database." (PMID 36330442, 2022). "In the present study, we demonstrated that G3BP1 expression was elevated in breast cancer and that knockdown of G3BP1 diminished the proliferation and metastasis of breast cancer cells." (PMID 36330442, 2022). "We further examined the correlation between circEIF3H and HSPD1/RBM8A/G3BP1 by qRT-PCT in 49 human breast cancer tissues and confirmed the positive correlation between circEIF3H and HSPD1/RBM8A/G3BP1 respectively." (PMID 35568705, 2022). "Our findings indicate that G3BP1 plays multiple roles in breast cancer cell proliferation and metastasis." (PMID 36330442, 2022).
breast carcinoma (continued). "Ras-GTPase-activating protein SH3 domain-binding protein 1 (G3BP1), a known oncoprotein, is overexpressed in a variety of human cancers, such as breast cancer, renal cell carcinoma, and hepatocellular carcinoma." (PMID 32978516, 2020). "Overexpression of G3BP1 has been shown to promote breast cancer cells proliferation and induce EMT transition." (PMID 29717134, 2018). "Our data indicated that G3BP1 downregulation suppressed primary tumor growth and lung metastasis of mouse 4T1 breast cancer cells." (PMID 25962958, 2015). "Despite previous reports demonstrating that G3BP1 was associated with cell motility and invasion, our study provided the first evidence that G3BP1 mediates the EMT in breast cancer cells." (PMID 25962958, 2015). "This indicates a novel role for G3BP1 in the regulation of cell proliferation in breast cancer cells, perhaps via a regulatory effect on PMP22 expression." (PMID 24321297, 2013). "In this study we identified PMP22 mRNA levels as being influenced by G3BP1 in breast cancer cell lines." (PMID 24321297, 2013). "Since G3BP1 has been reported to be a pro-survival factor, we evaluated if depletion of G3BPs can affect cell survival in breast cancer cells." (PMID 24321297, 2013). "It has been reported that G3BP1 could inhibit cell proliferation, and low G3BP1 levels enhanced mTORC1-driven breast cancer cell motility and correlate with adverse outcomes in patients." (PMID 38164170, 2024). "Furthermore, the invasive ability of breast cancer cells was significantly inhibited by reducing the expression of G3BP1." (PMID 36330442, 2022). "In breast cancer, G3BP1 supported cell proliferation via increasing PMP22 expression." (PMID 35568705, 2022). "We suggest SNORA71A enhances metastasis of breast cancer by binding to G3BP1 and stabilizing ROCK2." (PMID 35100495, 2022). "Accumulating evidence showed that HSPD1, RBM8A, and G3BP1 played a key role in tumor progression in several cancers; however, its effect on breast cancer proliferation and metastasis remains unclear." (PMID 35568705, 2022). "In this study, we demonstrated that G3BP1 was a key molecule regulating breast cancer cell proliferation and metastasis and that its role in breast cancer cells may be exerted by activating PKCζ." (PMID 36330442, 2022). "Taken together, these findings strongly suggested that HSPD1/RBM8A/G3BP1 could promote breast cancer progression and were correlated with poor prognosis." (PMID 35568705, 2022). "Expression of G3BP1 in benign breast and breast cancer tissues." (PMID 36330442, 2022). "To confirm this hypothesis, we detected an interaction between G3BP1 and PKCζ using co-immunoprecipitation assay in breast cancer MDA-MB-231 cells and found the co-localization of G3BP1 and PKCζ in the cells by confocal microscopy." (PMID 36330442, 2022). "In this study, we found that G3BP1 expression was upregulated in breast cancer." (PMID 36330442, 2022). "In this study, we found that knockdown of G3BP1 can inhibit the proliferation, invasion and metastasis of breast cancer cells, which suggests that G3BP1 may be a clinical therapeutic target." (PMID 36330442, 2022). "In conclusion, G3BP1 played multiple functions in breast cancer cell proliferation and metastasis." (PMID 36330442, 2022). "Moreover, the GEPIA database showed that the expression of G3BP1 had a significant positive correlation with the expression of ROCK2 in breast cancer." (PMID 35100495, 2022). "G3BP1 promotes proliferation of breast cancer cells and in a TSC2-deficient tumor model." (PMID 34778262, 2021). "In breast cancer, G3BP1 participated in the EMT and metastasis through regulating Smad signaling." (PMID 29717134, 2018).
breast carcinoma (continued). "Because G3BP1 is overexpressed during breast cancer, we aimed to investigate whether G3BP1 was involved in the EMT and to elucidate the mechanism by which G3BP1 regulates tumor metastasis in human breast cancer." (PMID 25962958, 2015). "Here, we demonstrated that the upregulation of G3BP1 activates the EMT in breast cancer cells." (PMID 25962958, 2015). "Here we show that G3BP1 is important for optimal breast cancer cell proliferation." (PMID 24321297, 2013). "Importantly, these miRNAs target genes associated with metastasis as NUCKS1, mainly in non-small cell lung and breast cancer, and androgen response, G3BP1, suggesting their potential role in suppressing the progression of tumors and enhancing therapy sensitivity." (PMID 40004509, 2025). "The knockdown of G3BP1 attenuated a series of metastasis-related properties of breast cancer cells, such as chemotaxis, migration, Golgi polarity localization, and actin polymerization, while the proliferation and invasive ability of breast cancer cells were also affected." (PMID 36330442, 2022). "Therefore, we hypothesized that G3BP1 might regulate EGF-stimulated breast cancer cell motility through PKCζ." (PMID 36330442, 2022). "However, the specific mechanism by which G3BP1 plays a role in breast cancer cell proliferation and metastasis remains unclear." (PMID 36330442, 2022). "Therefore, in this study, we hypothesized that G3BP1 participates in the EMT to induce tumor metastasis in human breast cancer." (PMID 25962958, 2015). "Thus, G3BP1 knockdown inhibited breast cancer metastasis to the lungs." (PMID 25962958, 2015). "We speculate that Smad3 is more crucial than Smad2/4 for the G3BP1-induced EMT in breast cancer." (PMID 25962958, 2015). "Additionally, G3BP1 is over-expressed in certain tumors such as breast cancers." (PMID 22205990, 2011). "A case in point is G3BP1’s degradation of peripheral myelin protein 22 (PMP22) mRNA to inhibit the expression of PMP22, which can promote the proliferation of breast cancer cell." (PMID 37179344, 2023). "For example, a study indicated that G3BP1 has an interaction with GSK-3β, contributing to promote breast cancer proliferation in vitro." (PMID 34967276, 2022). "The interaction of G3BP1 and GSK-3β inhibits the degradation of β-catenin in the cytoplasm and promotes the proliferation of breast cancer and esophageal cancer by enhancing the stability of β-catenin." (PMID 34526993, 2021). "Five genes (DPH2 G3BP1, G3BP2, NSUN2, and TTC17) were similarly regulated by SK1 KD in prostate and breast cancer cells." (PMID 30971929, 2019). "EGCG interacts with target proteins in the breast cancer cells, such as ERα, Zap-70, PI3K, G3BP1, IGF-1R, vimentin, Bcl-2, Bcl-xL, GRP78, and Fyn via hydrogen bonding, which plays a role in the inhibition of breast cancer." (PMID 27483305, 2016). "To determine whether G3BP1 affected tumor growth and lung metastasis in 4T1 cells in vivo, we constructed two stably G3BP1 shRNA-expressing clones (G3BP1(−)-1 and G3BP1(−)-2) by transfecting the pGU6/hygro-mus-shG3BP1 or pGU6/hygro-control vector into murine mammary carcinoma 4T1-luc cells." (PMID 25962958, 2015). "We found that G3BP1 to a larger extent than G3BP2 influences mRNA expression levels and breast cancer cell proliferation." (PMID 24321297, 2013). "Further, exploration of the role of G3BP1 in cellular signaling processes, showed the G3BP1 knockdown significantly inhibited the phosphorylation of Akt 473, integrin β1, and cofilin in EGF-induced breast cancer MDA-MB-231 cells as verified by western blot." (PMID 36330442, 2022). "These evidences support one of the SNORA71A mechanisms that it might recruit G3BP1 to the mRNA of ROCK2, thus increasing the mRNA stability of ROCK2, promoting thereby the EMT development of breast cancer by TGF‐β signaling." (PMID 35100495, 2022).
breast carcinoma (continued). "Furthermore, Kaplan–Meier survival analysis showed that breast cancer patients with high HSPD1, RBM8A, or G3BP1 expression respectively had significantly worse distant metastasis-free survival (DMFS) in the TCGA Cohort." (PMID 35568705, 2022). "However, G3BP1 inhibits the expression of peripheral myelin protein 22 (PMP22) mRNA, which plays a role in the regulation of breast cancer cell proliferation." (PMID 34526993, 2021). "G3BP1 mRNA levels are increased in mouse and human TSC tumors [angiomyolipomas (AML), subependymal giant cell astrocytoma (SEGA), subependymal nodules (SEN)] and in breast cancer." (PMID 34778262, 2021). "Moreover, our study not only elucidated the mechanism by which G3BP1 induces the EMT but also provided a potential therapeutic target for the invasion and metastasis of breast cancer." (PMID 25962958, 2015). "Both G3BP1 and G3BP2 are dramatically overexpressed in human cancers, especially breast cancer, suggesting that they may be related to cancer progression." (PMID 25962958, 2015). "In conclusion, our study demonstrates specific effects of G3BP1 and G3BP2 in breast cancer cells." (PMID 24321297, 2013). "Interestingly, increased expression of HIF1α and G3BP1, two YB-1 translational targets and elements of a stress-adaptive programme, mirrored the levels of YB-1 in both transformed primary and established MDA-MB-231 breast cancer cells." (PMID 34294889, 2022). "Our findings identified a novel function of G3BP1 in the progression of breast cancer via activation of the EMT, indicating that G3BP1 might represent a potential therapeutic target for metastatic human breast cancer." (PMID 25962958, 2015). "From analyses of the same three patient breast cancer datasets, we find HIF1A transcripts and its transcriptional targets, CAIX and VEGFA, and G3BP1 (but not NRF2) are all significantly higher in breast cancers that exhibit gain of function or amplified KRAS." (PMID 34294889, 2022). "Here, we show that G3BP1, but not G3BP2, supports proliferation of several breast cancer cell lines." (PMID 24321297, 2013). "We could only see effects on proliferation following G3BP1 depletion and not upon G3BP2 depletion, indicating that G3BP1 and G3BP2 may have different functions in breast cancer cells." (PMID 24321297, 2013). "Thus, G3BP1, but not G3BP2, seems to be a proliferation-promoting factor in breast cancer cells." (PMID 24321297, 2013).
lung cancer (22 papers, 2012 to 2025). A malignant neoplasm involving the lung. "Emerging studies in lung cancer have shown that lncP53RRA interacts with Ras GTPase-activated protein-binding protein 1 (G3BP1) in the cytoplasm." (PMID 38392340, 2024). "In lung cancer, it interacts with Ras GTPase-activating protein-binding protein 1 (G3BP1) in the cytosol." (PMID 35422492, 2022). "The elevated expression of G3BP1 confers a worse prognosis for patients with lung cancer after surgery." (PMID 34802443, 2021). "Several previous studies have noted that G3BPs (G3BP1 and G3BP2) are upregulated and associated with poor prognosis in human cancers including gastric, breast, lung cancer, sarcoma, prostate, hepatic, and colon cancer." (PMID 34521423, 2021). "For instance, a study showed that elevated expression of G3BP1 predicted poor prognosis in nonsmall cell lung cancer patients." (PMID 33726799, 2021). "Moreover, confocal results showed that cytoplasmic UTX co‐located with some SGs (G3BP1+ staining) in human lung cancer sections." (PMID 40536321, 2025). "In addition, G3BP1 has been shown to be involved in lung cancer cell migration and metastasis via Src/FAK signaling pathway." (PMID 29717134, 2018). "In lung cancer cell line H1299, KD of G3BP1 suppressed anchorage-independent cell growth." (PMID 23341773, 2013). "Further studies confirmed that EGCG inhibits Ras activation by blocking the interaction between G3BP1 and RAS-GAP, which ultimately plays an anticancer role in lung cancer." (PMID 37179344, 2023). "So far, there has been no report on the relationship between expression of G3BP1, p‐AKT, and YB1 and clinicopathological features/prognosis in surgically resected nonsmall cell lung cancer (NSCLC) patients." (PMID 31560169, 2019).